TOX (thymocyte selection associated high mobility group box)
Diseases named in the same sentence as TOX in open-access papers (continued):
Sharing a sentence is not in itself a finding about the gene and the disease.
cancer (60 papers, 2012 to 2026). A tumor composed of atypical neoplastic, often pleomorphic cells that invade other tissues. "Further research is needed to fully elucidate the molecular mechanisms underlying TOX's role in cancer, its interactions with AHR, and its potential as a therapeutic target in As3+-related carcinogenesis and other malignancies." (PMID 40303305, 2025). "Consistent with murine studies, well-known Tex genes (CTLA4, LAG3, HAVCR2 (gene encoding Tim-3), PDCD1, TIGIT, TOX) were among the most prominently represented in Tex from human cancers." (PMID 40236693, 2025). "We found that contact with a cancer cell was associated with higher expression of key activation markers (TOX and PD-1 for cytotoxic T cells; TOX and OX40 for T helper cells), and that T cells contacting cancer cells were much more likely to be proliferating." (PMID 37674077, 2023). "Increased TOX expression in PBLs from cancer patients was associated with reduced expression of anti-programmed cell death-1 (PD1)." (PMID 36005179, 2022). "However, in the case of chronic LCMV infections and cancer, TOX deficiencies had improved antiviral and anti-tumor activity, and were associated with decreased expression of CD8+ T cells suppressor receptors." (PMID 37355637, 2023). "Recent studies utilizing transcriptomics, mass cytometry, and epigenomics revealed a critical role of Thymocyte selection-associated high mobility group box protein (TOX) genes and TOX-associated pathways, driving T-cell exhaustion in chronic infection and cancer." (PMID 32823814, 2020). "In addition, TOX is also implicated in chronic infection and cancer." (PMID 36140731, 2022). "Based on previous studies, TBX21 (T-bet), PRDM1, and TOX have been reported to be transcriptionally regulated in neoantigen-specific TILs in cancer." (PMID 39870490, 2025). "GSEA indicated that TOX overexpression significantly activates cancer-related pathways, including EMT, glycolysis, myogenesis, and hypoxia." (PMID 40303305, 2025). "Enrichment analyses highlighted their involvement in cancer-related pathways, supporting the role of TOX in promoting CSC formation during As3+-induced carcinogenesis." (PMID 40303305, 2025). "In this study, we provide compelling evidence that AHR suppresses transformation as well as the possible formation of cancer stem-like cells (CSCs) induced by low-dose As3+ exposure through the transcriptional repression of TOX." (PMID 40303305, 2025). "TOX is a key transcription factor related to the development of malignant tumors and plays a significant role in T cells and other lymphocytes." (PMID 39758401, 2025). "TOX has emerged as a prominent regulatory factor for T cell dysfunction in malignant tumors in recent years." (PMID 39758401, 2025). "TOX is a transcription factor in cancer progression, and it has been shown that the downregulation of TOX in CD8+ T cells can enhance the antitumor effect of cells." (PMID 35250960, 2022). "Maternal CD8 T cells shared features of exhaustion with CD8 T cells from cancer and chronic infection, including transcriptional down-regulation of ribosomal proteins and up-regulation of TOX and inhibitory receptors." (PMID 34882194, 2022). "One set of observations here identified the NFAT/TOX/PD-1 transcriptional circuit as an exhaustion-driving mechanism in pregnancy, linking this pathway to T cell exhaustion arising in cancer and chronic infection." (PMID 34882194, 2022). "Transcription factors thymocyte selection-associated HMG box (TOX) and EOMES have been shown to promote T cell exhaustion in cancer and chronic viral infections." (PMID 36203601, 2022). "The TOX and its subfamily have been reported to be prognostic biomarkers in hematological malignancies and other cancers." (PMID 36005179, 2022). "TOX expression significantly increases immune infiltration levels and is downregulated in most cancer types." (PMID 35519421, 2022).
cancer (continued). "In cancer and chronic infection, TOX is expressed downstream of persistent NFAT signals driven by chronic antigen stimulation." (PMID 34882194, 2022). "In terms of avenues for potential future clinical translation, TOX should be tested as a new target for immunotherapy in cancer and infectious diseases to increase T cell functionality and counteract the dysfunctional immune response of CD8+ T cells." (PMID 35734162, 2022). "Consistently, IHC showed that TOX expression was lower in cancer cells but highly expressed in the TME." (PMID 33897695, 2021). "According to results from the Cancer Cell Line Encyclopedia database, compared with other cancers, TOX is highly expressed in ALL, particularly in T cell-ALL (T-ALL)." (PMID 33743809, 2021). "Altogether, these observations are critical in the context of cancer progression because TOX has been reported to have an oncogenic role by promoting cellular proliferation, metastasis and resistance to cellular death by apoptosis." (PMID 34220814, 2021). "This suggested that TOX is a key TF that promotes T cell exhaustion by inducing IC molecules in human cancers." (PMID 32111241, 2020). "Taken all these results together, we propose TOX as a positive regulator for T cell exhaustion and a predictor for anti-PD-1 responses in human cancer." (PMID 32111241, 2020). "The analysis of expression dynamics in single-cell trajectories, and the flow cytometry analysis of expression correlation demonstrated that TOX is a more influential regulator of CD8+ T cell exhaustion than other known factors in human cancer." (PMID 32111241, 2020). "A similar analysis was performed on our internal cohort of patients with NSCLC recruited from Yonsei Cancer Center in Korea, which revealed a similar inverse correlation between TOX expression level in the TI T cells and anti-PD-1 responses." (PMID 32111241, 2020). "This enabled the evaluation of differences in the overall survival between cancer patients exhibiting varying TOX expression levels in the TI T cells." (PMID 32111241, 2020). "In summary, our findings suggest that TOX is a prognosis‐related biomarker for multiple cancer types particularly LUAD." (PMID 32700817, 2020). "To evaluate the prognostic value of TOX in cancers survival, we comprehensively analyzed the correlations between TOX expression and survival in three large cancer databases comprising different extensive samples." (PMID 32700817, 2020). "TOX expression is frequently up-regulated in diverse types of cancer including breast cancer, lung cancer, cutaneous lymphoma, gastric cancer, leukemia, and central neural lymphoma." (PMID 32762688, 2020). "The relationships between TOX expression and immune infiltration in different cancers were investigated via TIMER and GEPIA2." (PMID 32700817, 2020). "TOX knockdown in the human TI CD8+ T cells resulted in downregulation of PD-1, TIM-3, TIGIT, and CTLA-4, which suggests that TOX promotes intra-tumoral T cell exhaustion by upregulating IC proteins in cancer." (PMID 32111241, 2020). "In summary, these results suggest that TOX expression level in the TI T cells can be used for patient stratification in cancer treatment, including anti-PD-1 immunotherapy." (PMID 32111241, 2020). "Base on the results hereinabove, the prognostic potential of TOX was verified using the RNA sequencing expression data of 33 cancer types from TCGA project in GEPIA2." (PMID 32700817, 2020). "Taken together, these observations suggest that TOX is a key regulator of terminally exhausted CD8+ T cell differentiation in human cancer." (PMID 32111241, 2020). "Deregulation of TOX expression in cancer can be roughly attributed to two mechanisms: genetic alteration and epigenetic events." (PMID 32762688, 2020). "The critical role of TOX in the development of CD8+ TEX in both chronic virus infections and cancer has only recently been described, with several studies identifying the necessity for TOX in TEX development." (PMID 31379821, 2019).
cancer (continued). "TOX was almost exclusively methylated in breast (43%) than lung (5%) cancer, whereas TOX3 was frequently methylated in lung (58%) than breast (30%) tumors." (PMID 22496870, 2012). "Interestingly, TOX is mostly known in the context of chronic infection and cancer, in which it plays the dual role of enhancing long-term survival of CD8+ T cells but also driving T cell hyperresponsiveness through exhaustion." (PMID 41022795, 2025). "TOX has been proven to have prognostic value in some malignant tumors." (PMID 39758401, 2025). "Exhausted CD8+ T cells are the major target of checkpoint blockade in patients with cancer and modulation of TOX, a transcription factor required for epigenetic remodeling and survival of functionally impaired exhausted T cells, has been suggested as a potential target for immunotherapy." (PMID 36911660, 2023). "TOX, a critical transcription factor related to the development of malignancies that contributing to lymphocytes not just T cells, had been proved prognostic value in some spectrum of cancers." (PMID 36434543, 2022). "As TOX and Nr4a transcription factors are critical for the transcriptional program of CD8+ T cell exhaustion downstream of NFAT, disruption of TOX and Nr4a expressions or activities could be promising strategies for cancer immunotherapy." (PMID 33728333, 2021). "TOX downregulates in most of the cancer types and correlates with poor prognosis in LUAD." (PMID 32700817, 2020). "As there was a correlation between TOX expression and TI CD8+ T cell exhaustion, we hypothesized that TOX expression in the TI T cells may be used as a clinical indicator during cancer treatment." (PMID 32111241, 2020). "Therefore, we suggest that TOX expression level in the TI T cells can be a useful predictor for anti-PD-1 efficacy in human cancer." (PMID 32111241, 2020). "Furthermore, the levels of TOX proteins correlated with the severity of intra-tumoral CD8 T cell exhaustion in human cancers." (PMID 33202877, 2020). "TOX is a prognosis‐related biomarker for multiple cancer types especially LUAD." (PMID 32700817, 2020). "TIMER was used to analyze TOX expression in different cancers." (PMID 32700817, 2020). "Future development of drug candidates inhibiting TOX–DNA interactions could follow previous studies where SMIs have been successfully developed via CADD to target the DNA-binding domains of other cancer drug targets, such as AR, ERG, and MYC." (PMID 31554191, 2019). "Thus, continuous TOX expression acts as a durable epigenetic barrier reinforcing Tex developmental fate, and manipulation of TOX even after Tex formation may provide therapeutic opportunities to reprogram Tex cells in chronic infection or cancer." (PMID 41194917, 2025). "Based on literature reviews, HMGA1, a chromatin-binding protein, has been linked to enhanced Wnt signaling in both intestinal stem cells and cancer stem cells 38, suggesting that TOX's oncogenic activity could involve chromatin interactions and stemness regulation." (PMID 40303305, 2025). "However, CD8+ T cells with TOX deficiency did not persist during chronic viral infection and cancer development." (PMID 37355637, 2023). "Additionally, nuclear factor TOX (thymus high-mobility group box protein) is a crucial regulator of the differentiation of tumor-specific T cells, and TOX-induced exhaustion program serves to prevent the overstimulation of T cells and activation-induced cell death in cancer." (PMID 33728333, 2021). "However, the correlations between TOX expression, prognosis, and immune infiltration in different cancers remain unclear." (PMID 32700817, 2020). "Interestingly, our findings suggest that TOX has dual functions that high expression level of TOX is positively correlated with better prognosis in multiple cancer types included LUAD and, meanwhile, induces T cells exhaustion which causes the inefficiency of antitumor immunity." (PMID 32700817, 2020).
cancer (continued). "In our study, we found that, after TOX knockdown, some proliferation and apoptosis-associated genes, such as PFKFB3, CDK5 and CKKN2A, were up- or down-regulated and most DEGs were enriched in cellular process and cancer pathways, which highlights the importance of TOX in cancer process." (PMID 31676945, 2020). "Considering concerns about the potential lack of specificity when directly manipulating TET2 in CAR T cells and TET2’s role in cancer, we compared the tissue-specific expression levels of TET2, TOX, and TOX2." (PMID 37467321, 2023). "Our results thus suggest a role for human TOX2, in contrast to exhaustion regulator TOX, as a potentiator of central memory differentiation of CAR T cells, with plausible utility in CAR T cell cancer therapy via modulated TOX2 expression." (PMID 37467321, 2023). "Consistent with the effects of FK506 on TEX cells in cancer and chronic infection, FK506 diminished the coexpression of TOX and PD-1." (PMID 34882194, 2022). "Therefore, some studies have revealed that TOX could predict prognosis in human cancer." (PMID 36434543, 2022). "A series of recent studies reported that TOX promotes CD8+ T cell exhaustion in chronic viral infection and cancer." (PMID 32111241, 2020). "To uncover potential features of CD4+ T-cell dysfunction in cancer and parallels with CD8+ T-cell exhaustion, we used the same marker profiles to investigate CD4+ T-cell subsets, which were identified by the expression of Tcf1/7 and TOX, respectively." (PMID 40897819, 2025). "Recently, it has been reported that TOX may be involved in promoting CD8+ T cell exhaustion and the development of various malignant tumors." (PMID 33743809, 2021). "Several studies also showed that TOX may have a role in mediating transcriptional and epigenetic reprograming that are critical for the exhausted CD8+ T cells responses in cancer." (PMID 32117960, 2020). "Similarly, TOX was shown to act as a key inducer of epigenetic changes driving CD8 T cell exhaustion in chronic infection and cancer." (PMID 33202877, 2020). "Recently, six studies have identified TOX as critical transcriptional and epigenetic coordinator of CD8+ T-cell exhaustion in response to T-cell receptor stimulation and NFAT activation in infection and cancer." (PMID 32106280, 2020). "Due to the lack of adjacent normal tissues, some cancer types are unable to show the change of TOX expression in tumorigenesis." (PMID 32700817, 2020). "Moreover, a minority of cancer types, such as BRCA, LGG and SKCM, also were found that their immune infiltration levels are significantly related to TOX." (PMID 32700817, 2020). "Extension of these assays to TOX, TOX3, and TOX4 genes that share similar genomic structure and protein homology with TOX2 revealed distinct methylation profiles by smoking status, histology, and cancer type." (PMID 22496870, 2012). "As TOX expression was positively correlated with the severity of CD8+ T cell exhaustion, we hypothesized that TOX is a positive regulator of the exhaustion process in human cancers." (PMID 32111241, 2020). "However, the relationships among TOX expression, prognosis, immune infiltration, and T cells function in different cancers types have not been comprehensively investigated." (PMID 32700817, 2020). "Here, we noticed that TOX has significant interactions with multiple key genes of exhausted T cell comprising PD‐1 (Cor = .11, P = .014), TIM‐3 (Cor = .18, P < .0001), TIGHT (Cor = .2, P < .0001) and CXCL13 (Cor = .16, P < .001), which play critical role on current cancer immunotherapy." (PMID 32700817, 2020).
cancer (continued). "Hence, the transcriptional interplay among NFAT, TOX, and NR4A protein families influences T-cell exhaustion and inhibition of these factors that promote T-cell exhaustion could have a role in improving effector functions in cancer immunotherapy." (PMID 40236693, 2025). "Thus, TOX may influence the function of CD8+ T cell, and predict prognosis for cancer patients." (PMID 39758401, 2025).